ASH2L (ASH2 like, histone lysine methyltransferase complex subunit)
Description:
Transcriptional regulator. Component or associated component of some histone methyltransferase complexes which regulates transcription through recruitment of those complexes to gene promoters. Component of the Set1/Ash2 histone methyltransferase (HMT) complex, a complex that specifically methylates 'Lys-4' of histone H3, but not if the neighboring 'Lys-9' residue is already methylated. As part of the MLL1/MLL complex it is involved in methylation and dimethylation at 'Lys-4' of histone H3. May play a role in hematopoiesis. In association with RBBP5 and WDR5, stimulates the histone methyltransferase activities of KMT2A, KMT2B, KMT2C, KMT2D, SETD1A and SETD1B.
Synonyms: ASH2L1; ASH2L2; ASH2; Bre2
Tractability: Small molecule: a structure with a bound ligand is known; a high-quality ligand is known. Antibody: the Human Protein Atlas places it where antibodies can reach. PROTAC: ubiquitination databases record sites on it; its protein half-life has been measured; a small molecule that binds it is known.
Gene: Protein-coding gene on chromosome 8 (38,105,493 to 38,144,124, forward strand). Ensembl gene ENSG00000129691.
Subcellular location: Nucleus
Subcellular location (Human Protein Atlas): Nucleoplasm; Plasma membrane
Pathways (Reactome):
Gene expression (Transcription): Epigenetic regulation of gene expression by MLL3 and MLL4 complexes; Formation of WDR5-containing histone-modifying complexes; MLL4 and MLL3 complexes regulate expression of PPARG target genes in adipogenesis and hepatic steatosis; RUNX1 regulates genes involved in megakaryocyte differentiation and platelet function
Developmental Biology: Activation of anterior HOX genes in hindbrain development during early embryogenesis; Differentiation of naive CD4+ T cells to T helper 2 cells (Th2 cells)
Signal Transduction: Deactivation of the beta-catenin transactivating complex; Formation of the beta-catenin:TCF transactivating complex
Chromatin organization: PKMTs methylate histone lysines
Disease: Loss of Function of KMT2D in MLL4 Complex Formation in Kabuki Syndrome
Immune System: Regulation of PD-L1(CD274) transcription
Gene Ontology:
Molecular function: beta-catenin binding; protein binding; transcription cis-regulatory region binding
Biological process: DNA damage response; positive regulation of cell population proliferation; response to estrogen; transcription initiation-coupled chromatin remodeling; hemopoiesis; regulation of gene expression
Cellular component: histone methyltransferase complex; MLL1 complex; MLL1/2 complex; MLL3/4 complex; nucleoplasm; nucleus; plasma membrane; Set1C/COMPASS complex
Genetic constraint (gnomAD): Loss-of-function variants: 22 observed, 59.38 expected, observed/expected ratio (o/e) 0.37, 90% interval 0.26 to 0.53. The upper end of that interval is the gene's LOEUF score, 0.53, which puts it in group 2 of 6, group 1 being the genes least tolerant of losing a copy. Missense variants: 453 observed, 641.54 expected, observed/expected ratio (o/e) 0.71, 90% interval 0.65 to 0.76. Synonymous variants: 232 observed, 237.91 expected, observed/expected ratio (o/e) 0.98, 90% interval 0.88 to 1.09.
Homologues: Orthologues: chimpanzee ASH2L (99% identical), macaque ASH2L (99% identical), dog ASH2L (97% identical), guinea pig ASH2L (97% identical), pig ASH2L (96% identical), rat Ash2l (95% identical), mouse Ash2l (84% identical), zebrafish ash2l (76% identical), tropical clawed frog ash2l (69% identical), Drosophila melanogaster ash2 (42% identical), Caenorhabditis elegans ash-2 (31% identical).
Diseases named in the same sentence as ASH2L in open-access papers:
ASH2L is named in the same sentence as 36 diseases in open-access papers, as found by Europe PMC text mining. Sharing a sentence is not in itself a finding about the gene and the disease. The quoted sentences say what the papers report.
breast carcinoma (9 papers, 2007 to 2026). "ASH2L upregulates GATA3‐induced transcription of ESR1 in breast cancer cells." (PMID 37974198, 2023).
pancreatic cancer (3 papers, 2019 to 2021). "Thus, we further analyzed whether the expression level of circ-ASH2L was associated with the survival rate of patients with pancreatic carcinoma." (PMID 31718694, 2019). "Therefore, by sponging miR-34a, circ-ASH2L enhanced the expression of Notch1, one of the oncogenic signals, leading to tumor progression and poor survival of patients with pancreatic cancer." (PMID 34439315, 2021). "circ-ASH2L was highly up-regulated in pancreatic cancer cells and tissues." (PMID 34439315, 2021). "Circ-ASH2L, circBFAR, ciRS-7, hsa_circ_001653, CircFOXK2, circ-LDLRAD3, and circ_0030235 act as oncogenes in pancreatic cancer." (PMID 34183642, 2021).
pancreatic ductal adenocarcinoma (3 papers, 2019 to 2023). An infiltrating adenocarcinoma that arises from the epithelial cells of the pancreas. "Circ-ASH2L also comes in handy in the diagnosis and progression of pancreatic ductal adenocarcinoma, as high circ-ASH2L expression was correlated with lymphatic invasion and the TNM (tumour, node, metastasis) stage, plus it was an independent risk factor for pancreatic patient survival." (PMID 37628760, 2023).
acute myelogenous leukemia (2 papers, 2019 to 2023). "Low expression of ASH2L protein correlates with a favorable outcome in acute myeloid leukemia." (PMID 37974198, 2023).
colorectal cancer (2 papers, 2023). A primary or metastatic malignant neoplasm that affects the colon or rectum.
diabetic nephropathy (2 papers, 2022 to 2024). "The epigenetic factor ASH2L has long been thought to be a transcriptional activator, but its function and involvement in diabetic nephropathy is still unclear." (PMID 36553510, 2022). "To explore whether ASH2L regulates diabetic nephropathy, we used immortalized mMCs exposed to high glucose." (PMID 36553510, 2022).
endometrial cancer (2 papers, 2020 to 2023). Primary or metastatic malignant neoplasm involving the endometrium (mucous membrane that lines the endometrial cavity). "ASH2L is involved in promotion of endometrial cancer progression via upregulation of PAX2 transcription." (PMID 37974198, 2023). "Recent studies have also shown that ASH2L may act as a coactivator of ERα and promote the progression of endometrial cancer." (PMID 33302406, 2020). "ASH2L was found to interact with ERα to regulate a subset of estrogen-induced target genes, such as the PAX2 (paired box 2) transcription factor gene, thereby promoting the proliferation and migration of endometrial cancer cells." (PMID 33302406, 2020).
glioblastoma (2 papers, 2023 to 2025). The most malignant astrocytic tumor (WHO grade IV). "To assess the role of ASH2L in more clinically-relevant settings, we tested the effect of ASH2L KO in patient derived primary glioblastoma cells, GBM4." (PMID 37974198, 2023). "To assess which SET1/MLL family complexes ASH2L is mainly part of in glioblastoma cells, we performed quantitative mass spectrometry (MS) of the ASH2L interactome for U373 and U87MG cell lines." (PMID 37974198, 2023). "TCGA analysis showed high ASH2L expression in glioblastoma compared to low grade gliomas and immunohistochemical analysis revealed significant ASH2L expression in glioblastoma tissues, attesting to its clinical relevance." (PMID 37974198, 2023). "Essentiality of WDR5 together with ASH2L for glioblastoma cells emphasizes the importance of WRAD module for cancer cell fitness." (PMID 37974198, 2023). "Mass spectrometry analysis revealed the interaction partners of ASH2L in glioblastoma cell lines as SET1/MLL family members including SETD1A, SETD1B, MLL1 and MLL2." (PMID 37974198, 2023). "Regulation of the transcriptome by ASH2L prompted us to analyze its localization on chromatin using CUT&RUN in glioblastoma cells." (PMID 37974198, 2023). "ASH2L-ablated glioblastoma cells had reduced tumor forming capacity in vivo and ASH2L expression was high in glioblastoma tissues, attesting to ASH2L’s clinical relevance." (PMID 37974198, 2023). "Using EpiDoKOL, we performed drop-out screens on multiple cell lines and identified ASH2L as an indispensable gene for glioblastoma cell survival." (PMID 37974198, 2023). "Collectively, these clinically relevant results illustrate that ASH2L plays a critical role in glioblastoma progression." (PMID 37974198, 2023). "Conversely, 94.1% of U87MG peaks and 66.4% of U373 peaks were common indicating direct targets of ASH2L in glioblastoma cells." (PMID 37974198, 2023). "The growth of ASH2L-depleted glioblastoma cells was markedly slower than controls in orthotopic in vivo models." (PMID 37974198, 2023). "Screens conducted in multiple cell lines revealed ASH2L, a histone lysine methyltransferase complex subunit, as a major regulator of glioblastoma cell viability." (PMID 37974198, 2023). "We next examined ASH2L protein in patient samples by immunohistochemistry utilizing a glioblastoma tissue microarray with 80 cores representing 40 different glioblastoma cases." (PMID 37974198, 2023). "Collectively, these results suggest that ASH2L plays a critical role in maintenance of glioblastoma cell fitness through regulating cell cycle progression." (PMID 37974198, 2023). "Among the genes validated for their essential function in glioblastoma, ASH2L was the least studied in cancer and its ablation gave a stronger phenotype; therefore we further investigated its role in glioblastoma." (PMID 37974198, 2023). "Together, we generated a model for the role of ASH2L in regulating multiple cellular phenotypes in glioblastoma cells, such as cell cycle, mitotic spindle formation and apoptosis." (PMID 37974198, 2023). "Together, we suggest that targeting ASH2L could serve as a new therapeutic opportunity for glioblastoma." (PMID 37974198, 2023). "Designing effective strategies to inhibit ASH2L, identified through our targeted screens as a novel regulator of tumor cell survival, can lead to development of successful therapeutic approaches for glioblastoma." (PMID 37974198, 2023). "To address the essential role of ASH2L for glioblastoma cell survival further, we focused our attention to chromatin modifying complexes, specifically, SET1/MLL family of histone methyltransferases SET1 (SETD1A), SET1B (SETD1B), MLL1 (KMT2A), MLL2 (KMT2B), MLL3 (KMT2C) and MLL4 (KMT2D)." (PMID 37974198, 2023). "Encouraging results obtained in primary GBM cells led us to investigate the role of ASH2L in glioblastoma growth in vivo." (PMID 37974198, 2023).
glioblastoma (continued). "The most significant phenotype was observed for U373 cells and we further delineated the effects of RBX1, ASH2L, SSRP1 ablation on glioblastoma cell fitness using this cell line." (PMID 37974198, 2023). "70% of glioblastoma specimens had strong ASH2L expression, whereas nonmalignant tissue specimens had none/low expression." (PMID 37974198, 2023). "Indeed, ASH2L expression was higher in glioblastoma in comparison to low grade gliomas (LGG-Grade 3 and Grade 3); ASH2L was expressed in all glioblastoma subtypes, but enriched for proneural subtype, based on TCGA." (PMID 37974198, 2023). "In our experiments, we chose to focus on characterizing the role of ASH2L, one of the four well-conserved core subunits of SET1/MLL family complexes, since it has not been previously studied in glioblastoma." (PMID 37974198, 2023).
Hodgkins lymphoma (2 papers, 2020 to 2023). A heterogeneous group of malignant lymphoid neoplasms of B-cell origin characterized histologically by the presence of Hodgkin and Reed-Sternberg (HRS) cells in the vast majority of cases. "ASH2L drives proliferation and sensitivity to bleomycin and other genotoxins in Hodgkin’s lymphoma and testicular cancer cells." (PMID 37974198, 2023). "Using a whole-genome CRISPR/Cas9 gene knockout approach, we identified ASH2L, a core component of the H3K4 methyl transferase complex, as a protein required for bleomycin sensitivity in L1236 Hodgkin lymphoma." (PMID 33257682, 2020).
Kabuki syndrome (2 papers, 2015 to 2023). Kabuki syndrome (KS) is a multiple congenital anomaly syndrome characterized by typical facial features, skeletal anomalies, mild to moderate intellectual disability and postnatal growth deficiency. "For example, while MLL1 does not interact with RbBP5 or Ash2L in pairwise experiments, an investigation of Kabuki syndrome missense mutations suggests that the MLL1 SET domain directly interacts with the RbBP5–Ash2L heterodimer within the context of the holocomplex." (PMID 36623730, 2023). "Analysis of Kabuki syndrome missense mutations when introduced into the MLL1 SET domain resulted in the identification of a surface, called the Kabuki interaction surface, that is required for interaction of MLL1 with the RbBP5/Ash2L heterodimer within the MLL1 core complex." (PMID 26324722, 2015).
liver cancer (2 papers, 2019 to 2025). An epithelial or non-epithelial malignant neoplasm that arises from the liver. "Moreover, mutation at position 312 of ASH2L significantly diminished the ability of AARS1 to enhance VEGFA expression in HCC cells, indicating that AARS1 promoted angiogenesis in liver cancer through ASH2L lactylation." (PMID 40726441, 2025). "Treatment with miR-34a has already entered a clinical trial in liver cancer, and ectopic circ-ASH2L may also be an important factor in the diagnosis and prognosis of PDAC." (PMID 31718694, 2019).
testicular cancer (2 papers, 2020 to 2023). A primary or metastatic malignant neoplasm that affects the testis. "Data from the Tumor Cancer Genome Atlas indicate that patients with testicular cancer carrying alterations in the ASH2L gene are more likely to relapse than patients with unaltered ASH2L genes." (PMID 33257682, 2020). "Knocking down ASH2L in these cells and in the NT2D1 testicular cancer cell line rendered them resistant to bleomycin, etoposide, and cisplatin but did not affect their sensitivity toward ATM or ATR inhibitors." (PMID 33257682, 2020).
atherosclerosis (1 paper, 2024). A disease characterized by the build-up of fatty material and calcium deposition in the arterial wall resulting in partial or complete occlusion of the arterial lumen. "Here we found that ECs-specific Ash2l knockdown could alleviate atherosclerotic lesions in both en-face and cross-sectional area in high-cholesterol diet ApoE−/− mice, confirming Ash2l deficiency could prevent atherosclerosis." (PMID 38280036, 2024). "Collectively, our findings identify Ash2l as a novel regulator that mediates endothelial injury and atherosclerosis." (PMID 38280036, 2024). "In this study, we identified that Ash2l as an important regulator in the process of atherosclerosis, enhanced the expression of scavenger receptors through the activation of PPARγ." (PMID 38280036, 2024). "Because lipid metabolism contributed significantly to atherosclerosis, we next examined the effects of Ash2l on multiple metabolic parameters in mice fed with normal chow or high cholesterol diet for 12 weeks." (PMID 38280036, 2024). "Considering endothelial injury and dysfunction were typical features of early atherosclerotic lesions, we detected Ash2l expression changes on the ECs of aortic sinus plaques from high-cholesterol diet-fed ApoE−/− mice, an animal model for atherosclerosis." (PMID 38280036, 2024). "Ash2l, therefore, represents a potential intervention for atherosclerosis-mediated endothelial dysfunction." (PMID 38280036, 2024). "In our present study, we identified that epigenetic factor Ash2l participated in the pathogenesis of atherosclerosis by aggravating vascular inflammation, promoting the uptake of oxidized lipids in ECs and weakening permeability barrier function." (PMID 38280036, 2024). "In sum, these results suggested that oxLDL enhanced the interaction between CD36 and TLR4 in ECs and further triggered NF-κB signal transduction, which was related to the effect of Ash2l in promoting atherosclerosis." (PMID 38280036, 2024). "Indeed, Ash2l-overexpressed ECs enhanced Dil-oxLDL uptake, pointing to aggravation of atherosclerosis upon Ash2l overexpression." (PMID 38280036, 2024). "Targeting Ash2l may provide valuable insights for developing novel therapeutic candidates for atherosclerosis." (PMID 38280036, 2024). "Loss of Ash2l abundance at the promoter of PPARγ inhibited CD36 transcription, which significantly weakened the proximity ligation signals between TLR4 and CD36, thus reducing NF-κB signal activation and contributing to the protection against endothelial injury and atherosclerosis." (PMID 38280036, 2024). "We also detected high expression of Ash2l in oxLDL induced ECs, while Ash2l knockdown significantly reduced the expression of scavenger receptors and the uptake of oxidized lipid, which might be an effective way to counteract atherosclerosis." (PMID 38280036, 2024). "We firstly determine whether knocking down of Ash2l has an anti-atherosclerosis effect." (PMID 38280036, 2024). "However, the role of Ash2l in atherosclerosis has not yet been fully elucidated." (PMID 38280036, 2024).
cervical cancer (1 paper, 2023). A primary or metastatic malignant neoplasm involving the cervix. "ASH2L is highly expressed in cervical cancer, and its depletion inhibits HeLa cell proliferation." (PMID 37974198, 2023).
embryonal carcinoma (1 paper, 2020). A non-seminomatous malignant germ cell tumor characterized by the presence of large germ cells with abundant cytoplasm resembling epithelial cells, geographic necrosis, high mitotic activity, and pseudoglandular and pseudopapillary structures formation. "Moreover, among these six pairs of ASEs, only alternative promoters of ASH2L have been reported in embryonal carcinoma." (PMID 33101358, 2020).
endothelial dysfunction (1 paper, 2024). In vascular diseases, endothelial dysfunction is a systemic pathological state of the endothelium (the inner lining of blood vessels) and can be broadly defined as an imbalance between vasodilating and vasoconstricting substances produced by (or acting on) the endothelium. "More importantly, Ash2l knockdown was associated with reduced scavenger receptors, which decreased the uptake of lipids by ECs and further improved the endothelial dysfunction." (PMID 38280036, 2024). "To investigate whether Ash2l was associated with endothelial injury, we treated primary cultured rat artery endothelial cells (RAECs) with oxLDL, a potent inflammatory agent which can induce endothelial inflammation and further lead to endothelial dysfunction." (PMID 38280036, 2024).
esophageal carcinoma (1 paper, 2021). A primary or metastatic malignant neoplasm involving the esophagus. "Expression of the WRAD subunits ASH2L and RbBP5 was positively correlated with NORAD expression in esophageal carcinoma tissues." (PMID 34587992, 2021).
gastric cancer (1 paper, 2015). A primary or metastatic malignant neoplasm involving the stomach. "In the present study, we showed that components of WRAD (WDR5, RBBP5 and ASH2L) can inhibit proliferation of gastric cancer cells, suggesting that DPY30 act through the increased H3K4MT activity." (PMID 26147337, 2015).
hepatitis B (1 paper, 2019). "Moreover, correlations between the expression of ZNF479 and its downstream factors were more pronounced in HCC patients with hepatitis B. Here, we found that ZNF479 regulates MT-1 expression by modulating ASH2L in HCC." (PMID 31138789, 2019).
neuroblastoma (1 paper, 2009). Neuroblastoma (NB) is the most common solid, extracranial childhood tumor. "Here, we reduced levels of Ap2δ and Ash2l in the neuroblastoma cell line, Neuro2A, and analyzed their gene expression profiles using whole-genome mouse cDNA microarrays." (PMID 20046871, 2009).